INSR (insulin receptor)
Diseases named in the same sentence as INSR in open-access papers (continued):
Sharing a sentence is not in itself a finding about the gene and the disease.
diabetes (continued). "As PTP1B is a key regulator of insulin receptor signaling and plays an essential role in diabetes, PTP1B activity is coupled to the pain hypersensitivity associated with diabetes recently." (PMID 38334011, 2024). "Insulin-stimulated signaling pathways regulate insulin receptor substrate (IRS) activity in various tissues, including muscle and pancreatic beta cells, and have been identified as a pathogenic factor in diabetes onset (Yiannakouris, 202)." (PMID 38694942, 2024). "Vitamin D deficiency and type 2 diabetes mellitus are risk factors for colorectal cancer, suggesting a role for vitamin D receptor (VDR) and insulin receptor (INSR) gene polymorphisms." (PMID 39201651, 2024). "In metabolic disorders such as obesity and diabetes, individuals often exhibit reduced surface insulin receptor (INSR) content and diminished INSR kinase (IRK) activity, which are essential for proper insulin signaling." (PMID 39125938, 2024). "The A24D variant is associated with inefficient cleavage of preproinsulin, whereas the V92L variant weakens the affinity of insulin for insulin receptor, and both lead to mutant INS gene–induced diabetes of youth." (PMID 36983642, 2023). "The action of vitamin D on the insulin receptor in beta cells is proposed as a potential mechanism linking vitamin D to diabetes." (PMID 38179344, 2023). "Some, such as thyroid adenoma associated (THADA) and insulin receptor (INSR), are associated with metabolic disorders in PCOS and type 2 diabetes mellitus (T2DM), and others with high bioavailable (unbound) circulating T levels." (PMID 37834765, 2023). "Investigation of the detailed regulatory action of KIAA1324 between GRP78 and INSR would provide deeper insight into cancer progression and other diseases including diabetes." (PMID 37612293, 2023). "Further, INSR expression changes in the kidney during diabetes, indicating that it contributes to DKD of type 2." (PMID 37063851, 2023). "For instance, signaling by insulin receptor was found to be mouse-specific in aorta, but the diabetes pathway was impaired in both mouse and human liver." (PMID 38060277, 2023). "These ischemic gastrocnemius muscles manifested less leukocyte functionality and more diabetes and aging-related pathways (Insulin Receptor Signaling, Cardiac Hypertrophy, Sirtuin Signaling, and White Adipose Tissue Browning)." (PMID 36821386, 2023). "In contrast, activation of the insulin receptor by PGG to facilitate diabetes intervention requires higher doses up to 100 μM." (PMID 35409415, 2022). "Diabetes mellitus (DM) is a common metabolic disorder characterized by high plasma glucose over a long period due to defects in insulin synthesis, insulin receptor, or postreceptor signaling pathway events." (PMID 35186807, 2022). "The hippocampus, associated with memory, is one of the areas with the highest concentrations of the insulin receptor (IR), which links diabetes to AD." (PMID 36012526, 2022). "Some macroelements such as Mg and Fe and certain trace elements such as B, Cr, Cu, Zn, and Cd enhance insulin action by activating insulin receptor sites, thus playing a specific role in the pathogenesis of diabetes and dyslipidemia." (PMID 35310037, 2022). "Although experiments in vitro and in mouse models of diabetes suggest a potential role of GM3 in competing with the insulin–insulin receptor interaction and to contribute to T2D, robust evidence using GM3 synthase specific inhibitors is needed." (PMID 36499769, 2022). "Mice with haploinsufficiency of insulin receptor (Insr+/− mice) exhibit metabolic dysfunctions of human diabetes, such as glucose intolerance and insulin resistance." (PMID 35207132, 2022). "Insulin receptor plays an important role in diabetes-related pathways, and diabetes mellitus usually shows abnormal number and affinity of insulin receptor." (PMID 36559019, 2022). "Given these attributes, InsR sensitizers represent an opportunity to develop a new type of therapeutic drug to treat diabetes." (PMID 35502441, 2022).
diabetes (continued). "Healthy fertile subjects had 23.82 timeshigher expression of the INSR gene than the fertile oneswith diabetes (P<0.0001, 95% CI: 2.207-4.293) and13.83 times higher IRS-1 gene (P<0.0001, 95% CI:0.679-1.813)." (PMID 36273315, 2022). "Upregulation of insulin receptor signaling is a promising approach to treat obesity and diabetes, and the action of glucose-lowering agents, such as GLP-1 and extendin-4, is usually accompanied by the increased Irs2 expression." (PMID 36297523, 2022). "Increased serum levels of TNF-α have been accompanied by diabetes development, as it is known to interfere with signal transduction mediated by insulin receptor that leads to the inhibition of the insulin effect." (PMID 35335970, 2022). "Insulin receptor (InsR) sensitizers represent a new type of therapeutic agent for the treatment of diabetes, with 2′-O-methylperlatolic acid (2-O-M) being a potential InsR targeting drug." (PMID 35502441, 2022). "In the present study, women with diabetes in both groups had a low-levelexpression of INSR and IRS-1 genes compared to healthysubjects." (PMID 36273315, 2022). "TNF-α is a major protein related to obesity that plays an important role in regulating fat metabolism; it is positively correlated with obesity and inhibits intracellular signaling from the insulin receptor, leading to diabetes." (PMID 35409375, 2022). "The cleavage of the insulin receptor by β-secretase 1 (BACE1) in the liver increases during diabetes, which contributes to reduce insulin receptor levels and impair insulin signaling." (PMID 34029592, 2021). "In patients with diabetes, their insulin receptor is inhibited under stress, the oxidative metabolism of glucose is abnormal, and the negative nitrogen balance is more stubborn and obvious." (PMID 34526075, 2021). "In previous studies, researchers found that the level of the soluble truncated form of INSR in the plasma of patients with diabetes is much higher than that of control groups." (PMID 33947097, 2021). "In pancreatic β-cells, CAV1 plays a role in insulin receptor-mediated signaling, insulin secretion, and probably in diabetes." (PMID 34001235, 2021). "The analysis of adipose-derived exosomes miRNA content pre- and post-gastric bypass showed upregulation of miR103-3p which was known to target the insulin receptor signaling pathway and was previously found to be downregulated in diabetes." (PMID 33784999, 2021). "The amount of biologically active full-length INSR in the liver is reduced during diabetes, which can be partially restored with the presentation of BACE1 inhibitors." (PMID 33947097, 2021). "Diabetes was induced preconceptionally via doxycycline-induced knock down of the insulin receptor in transgenic rats." (PMID 34537857, 2021). "Further, digoxin that targets TNF and ceritinib that inhibits INSR are found to be potential drugs to manage COVID-19 patients having pre-existing diabetes." (PMID 34067609, 2021). "Unfortunately, molecules that are known to bind to IGF1R also bind to the closely related insulin receptor (InsR) and can disrupt metabolism in a fashion similar to diabetes." (PMID 34191793, 2021). "Impaired insulin receptor activities lead to IR, the key factor in the pathology of metabolic disorders including diabetes." (PMID 34163433, 2021). "In pancreatic β-cells, CAV1 plays a role in insulin receptor- (IR-) mediated signaling, insulin secretion, and possibly in diabetes." (PMID 32082483, 2020). "After exclusion of PCOS cases with a family history of diabetes, hypertension, or dyslipidemia, the phenotype-genotype correlations between the genes INSR and TOX3 and MS or IR were still significant (P < 0.05)." (PMID 32425888, 2020). "Finding a small molecule which can selectively activate INSR signaling in an insulin-independent manner represents a novel treatment for diabetes, including T2D." (PMID 31378829, 2020).
diabetes (continued). "This enrichment pathway analysis result indicates that insulins can bind to INSR on the cell membrane, and affect the occurrence of diabetes and inflammation through PI3K–AKT signal transduction pathway." (PMID 32265717, 2020). "In their study, insulin receptor was not only highly expressed, but it also had gains in copy number in patients with diabetes and RCC and in patients with diabetes only." (PMID 33008076, 2020). "As we have shown in the retina from diabetic rats, diabetes significantly reduced insulin receptor and Akt phosphorylation in the db/db retina." (PMID 32432228, 2020). "Similar to the INSR gene mentioned earlier, IRS-2 is an insulin receptor substrate that is highly associated with diabetes and obesity and negatively controls alternative macrophage activation and allergic inflammation of the lungs." (PMID 32512817, 2020). "After magnesium supplementation, with high dose, we found a significantly increased level of insulin receptor MOD value (0.355±0.004) compared with the untreated diabetic rat MOD (0.345±0.003) in skeletal muscle tissues." (PMID 32952944, 2020). "For example, insulin receptor, upregulated by berberine, lowers the blood glucose level among patients with type 2 diabetes mellitus, whereas muscle-specific insulin receptor knockout mice elevate blood glucose level." (PMID 32581311, 2020). "For instance, berberine, an alkaloid used in traditional Chinese medicine to treat diabetes, upregulates INSR expression in a protein kinase D-dependent manner in cultured liver cells." (PMID 31795422, 2019). "Another study reported that the adipocyte-specific deletion of INSR and IGF-IR led to inability to maintain body temperature, lipodystrophy, severe diabetes and ectopic fat deposition compared to IGF-IR loss alone, with a modest effect on fat physiology." (PMID 30754657, 2019). "A previous report showed that the BER improves diabetes by an enhanced insulin receptor (IRS) expression." (PMID 31878261, 2019). "Tumor necrosis factor-α (TNF-α) reduces insulin receptor substrate tyrosine phosphorylation and is an important mediator of IR in obesity and diabetes." (PMID 31258478, 2019). "The expression of the insulin receptor (IR) in pancreatic β-cells plays an essential role in β-cell development and function during diabetes progression." (PMID 31382473, 2019). "The abnormality of INSR function in the pathogenesis of diabetes has highlighted the importance of understanding the comprehensive regulation of INSR and its downstream signaling events." (PMID 31658625, 2019). "Treatment of fanca-/- mice with the ROS scavenger Quercetin can mitigate diabetes and obesity prone phenotypes in part through regulation of insulin receptor signaling." (PMID 31461451, 2019). "Yet, all potently lower blood glucose in a zebrafish model of diabetes suggesting that, in cone snails, diverse strategies have evolved to bind to and activate the fish insulin receptor." (PMID 30747102, 2019). "Type 2 diabetes (T2D), also known as non-insulin dependent diabetes mellitus, is a metabolic disorder characterized by chronic high blood glycemia and insulin receptor resistance, sometimes in combination with relative insulin deficiency." (PMID 30766472, 2019). "The cross-talk between NGF and insulin pathways downstream the insulin receptor suggests novel potential therapeutic targets to slow cognitive decline in AD and diabetes-related brain insulin resistance." (PMID 29736736, 2019). "In the baseline cross-sectional study, one SNP (rs758989) in GCK and four SNPs (rs7245757, rs1035942, rs1035940, and rs2042901) in INSR were selected as candidate SNPs that interact with alcohol to affect prediabetes and diabetes." (PMID 31882596, 2019). "Our findings suggest that cone snails have evolved diverse strategies to activate the vertebrate insulin receptor and provide unique insight into the design of novel drugs for the treatment of diabetes." (PMID 30747102, 2019).
diabetes (continued). "In mouse kidney, compared with wild type mice, either diabetes or NXT had little effect on INSR expression." (PMID 29904053, 2018). "Further, diabetes with CUMS exhibited a significant decrease in phosphorylation of insulin receptor and an increase phosphorylation of IRS-1 in brain." (PMID 30622594, 2018). "Understanding the structural biology of the insulin receptor and how it signals is of key importance in the development of insulin analogs to treat diabetes." (PMID 30356040, 2018). "We used the transgenic Tet29 diabetes rat model with an inducible knock down of the insulin receptor via RNA interference upon application of doxycycline (DOX) leading to insulin resistant type II diabetes." (PMID 29896157, 2018). "In type 2 diabetes mellitus patients, elevated GM3 levels cause insulin-receptor inactivation through a disorder in membrane microdomains, leading to insulin resistance." (PMID 29844375, 2018). "The results of Western blot validation showed that dynamic changes in proteins, such as IGF2, Ly6a, Grb10, and UBD, occurred to regulate the incidence of diabetes by influencing the insulin receptor substrate (IRS) signaling pathway." (PMID 30131712, 2018). "A recently discovered metabolic drug, metformin, which was originally employed to combat diabetes by acting on the liver, has been shown to interfere with insulin receptor signaling within pancreatic cancer." (PMID 29320425, 2018). "PTP1B is the known key enzyme that attenuates insulintransduction cascade by desensitizing the insulin receptor.Since diabetes is a multi-genic disorder, drugs designed to actagainst individual molecular targets cannot be effective." (PMID 29379255, 2017). "Insulin insensitivity, or decreases in insulin receptor signalling, leads to diabetes mellitus type 2." (PMID 26901760, 2016). "To date, in vitro cell culture and animal model studies of diabetes examining the effect of 1,25(OH)2D on beta cell function, insulin receptor gene expression, and glucose uptake are inconclusive." (PMID 27586865, 2016). "Few examples include PPARG mutation in familial partial lipodystrophy (FPLD3), INSR in Donahue syndrome and Type A insulin resistance, HNF4A in Maturity-Onset Diabetes of Young (MODY1), and INS in Diabetes-type hyperglycemia and hyperinsulinemia." (PMID 27376154, 2016). "Liver-specific p85α knockout also increased insulin sensitivity, while p85α haploinsufficiency protected mice with concomitant heterozygous knockout of the insulin receptor and Irs1 from overt diabetes." (PMID 27766312, 2016). "The main activity of INSR is persuading uptake of glucose and because of a decrease in insulin receptor signaling leads to diabetes mellitus type 2." (PMID 27840822, 2016). "Here, we chose Bm-INSR gene as an example to study the possibility of using B. mori as diabetes model." (PMID 25302617, 2014). "The ectodomain, called soluble insulin receptor (SIR) has been found elevated in patients with diabetes mellitus." (PMID 24995000, 2014). "It has been shown that people with decreased insulin receptor sensitivity (diabetes) have a higher prominence of transformed fast glycolytic fatigable muscle fibers." (PMID 24744911, 2014). "If insulin is excessive, insulin receptor sensitivity can be reduced, thereby reducing the ability to process glucose that is called non-insulin-dependent diabetes mellitus." (PMID 25177729, 2014). "Data show that diabetes decreases insulin receptor phosphorylation, while increasing IRS-1Ser307 phosphorylation." (PMID 24695399, 2014). "For instance, insulin receptor is involved in diabetes and also plays a role in cell proliferation and cancer." (PMID 25559614, 2014). "Diabetes-induced changes in growth factor binding protein 3 (IGFBP-3) and tumor necrosis factor alpha (TNFα) have been linked to decreased insulin receptor signaling in diabetic retinopathy." (PMID 24695399, 2014). "RNAi of Bm-INSR resulted in high percentages of black body color, which is similar in diabetes patients." (PMID 25302617, 2014).
diabetes (continued). "And as the association between AD and insulin resistance syndrome is gaining attention, insulin/insulin receptor-mediated signal transduction in diabetes is also worth further research." (PMID 24386004, 2013). "Structural studies elucidate how each of the three ligands, insulin, IGF-1, and IGF-2, interacts differently with isoforms A and B of the insulin receptor and with type I IGF receptor and explain how these protagonists contribute to diabetes-associated cancer." (PMID 23983688, 2013). "Taken together, these results suggest that diabetes decreases insulin receptor signaling in the retina, which likely involves TNFα levels." (PMID 23592917, 2013). "On the other hand, both JNK and p38MAPK signaling promotes diabetes by negatively regulating the function of insulin receptor." (PMID 23741327, 2013). "Reduction of the insulin receptor activity induced by diabetes was partially reversed by both ocular insulin administration and phloridzin treatment." (PMID 22046295, 2011). "Further analysis demonstrated that both normalization of hyperglycemia and increased ocular insulin signaling reversed diabetes-induced insulin receptor/Akt signaling defects." (PMID 22046295, 2011). "We and others have shown that diabetes depresses retinal insulin signaling with decreased kinase activities of the insulin receptor and downstream signaling proteins including Akt1 and Akt3." (PMID 22046295, 2011). "As target for a proof-of-principle experiment to establish inducible and reversible gene knockdown in rats we chose the insulin receptor (IR) mRNA in order to create a model for diabetes mellitus." (PMID 19340286, 2009). "We examined 35 genes predicted to have their major influence on insulin action, and three (9%)—INSR, PIK3R1, and SOS1—showed significant associations with diabetes." (PMID 14551916, 2003). "Similarly, in metabolic disease models, PGG enhances insulin receptor activation and glucose uptake, supporting its utility in glycemic regulation and diabetes management." (PMID 41194875, 2025). "Additionally, the rise in pro-inflammatory factors with aging disrupts insulin receptor signaling in adipose tissues, contributing to the development of diabetes and other metabolic diseases." (PMID 41237185, 2025). "Understanding the mechanisms underlying insulin action and the molecular interactions of ligands with the main human insulin receptor, hIR-B, is essential for developing more effective and safer therapeutic strategies for managing diabetes and related conditions." (PMID 40796375, 2025). "The results of GO biological function analysis showed that the chemical components of JA in the treatment of diabetes were mainly involved in the positive regulation of angiogenesis, insulin receptor signaling pathway, cell response to insulin stimulation, and other BPs." (PMID 41189218, 2025). "Specifically, we focused on the activation of p-INSR in STZ-induced diabetes model rats." (PMID 39885962, 2024). "Our case has some features of an INSR mutation; she has diabetes with hirsutism and oligomenorrhoea but no history suggestive of hyperinsulinaemic hypoglycaemia." (PMID 38461278, 2024). "Together, these findings support that insulin therapy in treated diabetics enhances the regulatory cascade downstream of the insulin receptor to activate AKT and that could potentially rescue β-cell functionality." (PMID 39684905, 2024). "Moreover, the kidney is vital in modulating lipid metabolism in vivo, and a marked reduction in insulin receptor expression was noted in the cortex of the kidney of high-fat diet-fed rats and in patients with diabetes mellitus type 2." (PMID 37951945, 2023).